NLRP3 (NLR family pyrin domain containing 3)
Diseases named in the same sentence as NLRP3 in open-access papers (continued):
Sharing a sentence is not in itself a finding about the gene and the disease.
hyperuricemia (continued). "Furthermore, treatment with allopurinol and notopterol from the second week post-hyperuricemia induction for four weeks attenuated cardiac dysfunction and suppressed NLRP3 activation and inflammatory cytokine production in cardiac tissue of hyperuricemic mice." (PMID 36986461, 2023). "Here, we summarize the cellular and molecular mechanisms by which uric acid may be involved in the activation of NLRP3 inflammasomes and provide new ideas for the pathogenesis of hyperuricemia in nephropathy." (PMID 35382689, 2022). "Innate immune pathways are also increasingly considered to play an important role in the pathogenesis of hyperuricemia, and particularly lead to activation of the NLRP3 inflammasome which contributes to the release of IL-1β and other pro-inflammatory cytokines." (PMID 34819865, 2021). "Therefore, inhibiting the TLR4 and NLRP3 pathways effectively reduced the release of inflammatory cytokines and at the same time attenuated the renal damage of hyperuricemia." (PMID 34444825, 2021). "The results showed that the expression of the NLRP3 inflammasome in peripheral blood mononuclear cells, and the levels of IL-1β and IL-18 in the plasma were upregulated in the gouty nephropathy group compared with the control and hyperuricemia groups." (PMID 34305953, 2021). "Taken together, these results support the hypothesis of hyperuricemia as a common detrimental condition that characterizes MS via the activation of the NLRP3/caspase-8 inflammasome pathway." (PMID 33670164, 2021). "More and more evidence indicate that uric acid-induced inflammation is the core mechanism of hyperuricemia rodent kidney injury, and the NLRP3 pathway may play a central role in it." (PMID 34987391, 2021). "Therefore, inhibition of the NLRP3 inflammasome is a feasible strategy to alleviate kidney inflammation and damage in hyperuricemia." (PMID 33959014, 2021). "Hyperuricemia-induced autophagy and NLRP3-dependent inflammation are critically involved in the development of renal damage and, therefore, highlight the inhibition of autophagy and inflammation in search of therapeutic strategies to treat uric acid nephropathy." (PMID 33648977, 2021). "We next examined whether reducing TLR6 level with adenovirus was able to restore myocardial damage and to inhibit NLRP3 inflammasome activation in rats bearing hyperuricemia." (PMID 32558367, 2020). "Therapeutic strategies reducing NLRP3 activation and/or lowering hyperuricemia could be useful in the therapy of PPMS." (PMID 29780394, 2018). "We previously reported that mitochondrial ROS is crucial for the activation of the NLRP3 inflammasome in macrophages by hyperuricemia in type 2 diabetic nephropathy and the mitochondrially targeted antioxidant, Mito-TEMPO, attenuated NLRP3 increase, and IL-1β release." (PMID 30483252, 2018). "Based on these data is tempting to speculate that, in PPMS, hyperuricemia would be responsible for the chronic activation of NLRP3 inflammasome and, as a consequence, the persistent activation of NF-Kb and an excessive generation of pro-inflammatory cytokines." (PMID 29780394, 2018). "Activation of TLR4 and the NLRP3 inflammasome promotes the maturation and release of caspase-1, along with downstream cytokines such as IL-1β and IL-18, triggering a persistent pro-inflammatory state crucial for the continued progression of hyperuricaemia nephropathy." (PMID 38041694, 2023). "Activation of TLR4 indirectly promotes the assembly of the NLRP3 inflammasome by regulating the nuclear factor kappa B (NF-κB) signaling pathway, thereby amplifying the inflammatory process and playing a significant pro-inflammatory role in hyperuricaemia nephropathy." (PMID 38041694, 2023).
hyperuricemia (continued). "Uric acid is the major antioxidant in the blood; therefore hyperuricemia could result in alterations in the extracellular redox environment that could impact on the responsiveness of monocytes to priming and activation of the NLRP3 inflammasome." (PMID 30761138, 2019). "Thus, hyperuricemia may also contribute to neurodegenerative diseases by activating the NLRP3 inflammasome." (PMID 24511458, 2013). "In a mouse model of hyperuricemia induced by potassium oxalate, SMM downregulated the expression of NLRP3, ASC, and caspase-1, as well as the secretion of IL-1β and IL-18." (PMID 40841164, 2025). "UA drives excretion through the activation of signaling cascades involving NLRP3, PI3K/Akt and MAPK, leading to the augmentation of PDZK1 and ABCG2 expression, thereby mitigating the effects of hyperuricemia." (PMID 38094893, 2023). "Therefore, we strongly suggest that xanthine can induce hyperuricemia in the kidney and inflammation in liver through the activation of NF-κB/NLRP3 inflammasome pathway; whereas strictinin supplementation can reduce UA production and inflammation through modulating NLRP3 inflammasome pathway." (PMID 36829604, 2023). "Polydatin has also been shown to inhibit NF-κB/NLRP3 through the AMPK/SIRT1 pathway, thereby reducing potassium oxonate-induced hyperuricemia and renal inflammation." (PMID 36632457, 2023). "The results showed that the protein expression levels of NLRP3, Caspase-1, and ASC were significantly increased in both renal tissues of hyperuricemia mice and adenosine-treated HK-2 cells." (PMID 36120294, 2022). "For example, in hyperuricemia, pyroptosis in human umbilical vein endothelial cells (HUVEC) can be promoted by regulating NLRP3 expression." (PMID 36304156, 2022). "Medium - and high-dose groups also reduced NLRP3, ASC, and Caspase-1 protein overexpression in hyperuricemia model cells." (PMID 36120294, 2022). "Potassium oxonate-induced hyperuricemia mice developed the elevated levels of liver XOD and renal ASC, Caspase-1, NLRP3, and GLUT9 protein and depressed OAT1 and OAT3 protein levels (all p < 0.05) compared with normal control mice." (PMID 36120294, 2022). "After the cells are stressed, various organelles in the cell become dysfunctional and participate in the NLRP3 inflammasome activation process, thereby affecting the occurrence and development of CKD in hyperuricemia." (PMID 35382689, 2022). "Patients with hyperuricemia activate the self-inhibited inactive NLRP3 through MSU as an activation signal that is recognized and bound by the leucine-rich repeat (LRR) of NLRP3." (PMID 34987391, 2021). "The results showed that the protein expression levels of NLRP3, caspase‐1, GSDMD‐FL and GSDMD‐N in kidney tissue from hyperuricaemia mice were significantly higher than those in kidney tissue from mice in the saline control group." (PMID 34296520, 2021). "In conclusion, we demonstrated that in hyperuricaemia, lncRNA‐HOTAIR promotes endothelial cell pyroptosis by competitively binding miR‐22 to regulate NLRP3 expression." (PMID 34296520, 2021). "For example, Shizhifang effectively suppresses the NLRP3-ASC-caspase-1 axis through accommodating the ROS pathway, thereby alleviates potassium oxonate - induced hyperuricemia." (PMID 33568990, 2020). "Hyperuricemia has been reported to induce renal inflammation through multiple mechanisms, including activation of JNK signaling pathway and NLRP3 inflammasome." (PMID 32116724, 2020). "The NLRP3/caspase-8 inflammasome pathway is activated in PPMS, possibly as a consequence of hyperuricemia." (PMID 29780394, 2018). "Uric acid (UA) activates the NLRP3-ASC-caspase-1 axis and triggers cascade inflammatory that leads to hyperuricemic nephropathy and hyperuricemia-induced renal tubular injury." (PMID 29358971, 2017).
hyperuricemia (continued). "To empirically elucidate the mechanisms underlying the effects of SZF on renal function, we used SZF to treat rats with mild hyperuricemia and then examined the interference of SZF on the NLRP3 signalling pathways in their kidneys." (PMID 29358971, 2017). "For example, L. rhamnosus Fmb14 has been shown to alleviate hyperuricemia-induced hepatocyte pyroptosis by inhibiting the NLRP3 inflammasome cascade, but it does not exhibit notable nucleoside degradation or XOD inhibitory capabilities." (PMID 41227678, 2025). "Increases hypoxanthine phosphate ribose transferase expression.Inhibits the uric acid synthesis by activating uric acid transporter.Inhibits NLRP3 inflammasome and TLR4/MyD88/NF-κB pathway.Regulates the composition and abundance of gut microbiota during hyperuricemia and renal inflammation." (PMID 36506033, 2022). "Tissue immunofluorescence results indicated that the expression of NLRP3, caspase‐1 and GSDMD‐FL was distributed throughout the glomeruli of the hyperuricaemia group; the glomerular fluorescence intensity in the hyperuricaemia group was significantly higher than that in the control group." (PMID 34296520, 2021). "For example, in hyperuricemia mouse model, nuciferine inhibited renal inflammation through suppression of Toll-like receptor 4/myeloid differentiation factor 88/NF-κB signaling and a NOD-like receptor family, pyrin domain containing 3 (NLRP3) inflammasome." (PMID 30360404, 2018). "Expression of NLRP3 and ASC-speck protein was significantly increased in PPMS, SMS, and AMS patients, but IL-18 and caspase-8 production was significantly increased only in PPMS, in whom a direct correlation between hyperuricemia and caspase-8 was detected." (PMID 29780394, 2018). "However, research on the specific mechanism of hyperuricemia and NLRP3 inflammasome activation is not clear." (PMID 35382689, 2022). "Given that anserine decreased the expression of TLR4/MyD88/NF-κB and NLRP3 and elevated Nrf2 and TIMP1 in hyperuricemic rats, we speculate that anserine improves overall kidney function by decreasing inflammation, oxidative stress and cellular damage in hyperuricemia." (PMID 36839325, 2023).
Anxiety (88 papers, 2017 to 2026). Intense feelings of nervousness, tension, or panic often arise in response to interpersonal stresses. "Male rats exposed to 21 days of CUS developed depressive- and anxiety-like behaviors, weight loss, and gut alterations, with a significant upregulation of NLRP3 in both serum and cecal mucosa." (PMID 41357236, 2025). "In summary, pharmacological inhibition of NLRP3 exerts a similar effect as NLPR3 deficiency on anxiety-like behavior." (PMID 36539796, 2022). "During alcohol withdrawal, NLRP3 deficiency attenuated anxiety-like behavior and neuronal injury in the mPFC and striatum." (PMID 36539796, 2022). "HFS stimulation of corticostriatal circuits rescued the NLRP3 deficiency-induced reduction in anxiety-like behavior, providing a link between NLRP3 signaling and glutamatergic transmission." (PMID 36539796, 2022). "After binge and gavage drinking of alcohol-induced anxiety behavior, NLRP3 deficiency prevented neuronal injury in both the mPFC and striatum, which is consistent with reports that activation of inflammation results in neuronal damage." (PMID 36539796, 2022). "Taken together, these data suggest that NLRP3 deficiency decreases binge drinking-induced anxiety-like behavior." (PMID 36539796, 2022). "Having shown that NLRP3 deficiency decreases binge drinking-induced anxiety-like behavior, we asked about the specific inflammatory response mechanism behind it." (PMID 36539796, 2022). "After anxiety-like behavior, NLRP3 deficiency reduced the presynaptic release of glutamate in the striatum, suggesting that NLRP3 affects glutamatergic transmission in the cortex and modulates anxiety-like behavior." (PMID 36539796, 2022). "Taken together, NLRP3 deficiency decreased glutamatergic transmission in corticostriatal circuits and decreased anxiety-like behavior." (PMID 36539796, 2022). "After the same amount of alcohol exposure in the gavage session, NLRP3 deficiency prevented withdrawal-induced anxiety-like behavior in the open field test and EPM." (PMID 36539796, 2022). "Scopolamine treatment showed significant increase in the level of anxiety and impairments in memory and cognitive function associated with increased level of pro-inflammatory cytokines and NLRP3 inflammasome components." (PMID 33863952, 2021). "This innovative research has revealed the antidepressant and anti-anxiety effects of Xiaoyaosan through its effect on endotoxin metabolism disorder caused by intestinal flora and the excessive activation of the NLRP3 inflammasome." (PMID 33935710, 2021). "For further studies, we demonstrated that both genetic knockout and pharmaceutical inhibition of the NLRP3 inflammasome remarkably enhanced the extinction of contextual fear memory and attenuated anxiety-like behavior caused by electric foot shocks." (PMID 32635937, 2020). "Both genetic knockout and pharmaceutical inhibition of the NLRP3 inflammasome enhance the extinction of contextual fear memory and attenuate anxiety-like behavior caused by electric foot shocks." (PMID 32635937, 2020). "The present study shows that stress accumulation causes an increase in extracellular ATP, the assembly of NLRP3 inflammasome, the cleavage of caspase-1, mature of IL-1β in the hippocampus as well as the depressive-like and anxiety-like behaviors in rodents." (PMID 28486969, 2017). "It is interesting to note that the NLRP3 inflammasome is also implicated in numerous mental illnesses, including anxiety- and depressive-like behaviors linked to spinal cord injuries or persistent inflammation, and in the cognitive deficiencies related to Alzheimer’s." (PMID 40002330, 2025). "Moreover, acetyl l-carnitine ameliorated the depressive-like anxiety behaviors induced by LPS by causing a decline in the NF-κB and NLRP3 inflammasome expression." (PMID 37994991, 2024). "NLRP3 deficiency decreased binge alcohol intake and binge drinking-induced anxiety-like behavior." (PMID 36539796, 2022).
Anxiety (continued). "It has been widely verified that frequent bouts of intoxication/withdrawal of binge drinking causes anxiety; however, whether NLRP3 is involved in binge drinking-induced anxiety behavior remains unclear." (PMID 36539796, 2022). "NLRP3 deficiency reduced excessive drinking in mice exhibiting anxiety-like behaviors." (PMID 36539796, 2022). "The mechanism underlying the anti-anxiety-like effect of gelsemine may be to protect neurons by suppressing the occurrence and development of inflammation by modulating the NLRP3 and CREB/BDNF pathways." (PMID 35203954, 2022). "In addition, pharmacological administration of the NLRP3 inhibitor MCC950 has the same effect as NLRP3 deficiency on anxiety-like behavior." (PMID 36539796, 2022). "Importantly, in vivo optogenetic induction of LTP or LTD in corticostriatal circuits (mainly mPFC-striatum) revealed that NLRP3 deficiency drove glutamatergic transmission, thereby affecting withdrawal anxiety-like behavior." (PMID 36539796, 2022). "Importantly, in vivo optogenetic induction of long-term potentiation (LTP) of corticostriatal circuits reversed the effects of NLRP3 deficiency on glutamatergic transmission and anxiety behavior." (PMID 36539796, 2022). "The protocol of 900 pulses for optogenetic LTD was applied in corticostriatal circuits and we found that induction of LTD decreased glutamatergic transmission and anxiety-like behavior, indicating a link of the NLRP3 deficiency-induced reduction of alcohol withdrawal anxiety-like behavior." (PMID 36539796, 2022). "Moreover, release of IL-1 is inhibited by FDP-derived metabolites, and NLRP3-deficient animals show anxiety reduction in response to prolonged sleep deprivation." (PMID 36620464, 2022). "Our results demonstrate that NLRP3 deficiency decreases binge alcohol intake and anxiety-like behavior through downregulation of glutamatergic transmission in corticostriatal circuits, which may provide an anti-inflammatory target for treating alcohol use disorders." (PMID 36539796, 2022). "A multitude of studies has shown a robust link between the activation of the NLRP3 inflammasome and behaviors that resemble anxiety." (PMID 40509387, 2025). "For instance, chronic mild stress significantly increases the expression of both the Nlrp3 inflammasome and IL-1β in the hippocampus, resulting in depressive- and anxiety-like behaviors in rats." (PMID 41276822, 2025). "Collectively, our findings indicate that BPA triggers anxiety-like behaviors and pyroptotic death of nerve cells via the NF-κB/IL-1β/NLRP3/Caspase-1 pathway." (PMID 38941031, 2025). "(2023) showed that acute alcohol exposure in adolescent and young adult rats activated NLRP3 in the basolateral amygdala only in males, inducing GABAergic inhibition and anxiety-like behaviors, while females remained unaffected." (PMID 41357236, 2025). "In animal studies, the inhibition of the NLRP3 inflammasome improves anxiety-like behavior and deficits in spatial learning and memory." (PMID 40565126, 2025). "In addition, the drop of estrogen levels may be a trigger for migraine in women and the activation of the NLRP3 inflammasome in the hippocampus caused by estrogen deficiency has been demonstrated in animal studies to contribute to anxiety-like behavior in female rodents." (PMID 39917435, 2024). "PTL improved motor, locomotor, cognitive and anxiety-like behaviours, restored neuronal integrity, upregulated Nrf2, and inhibited NLRP3 inflammasome, NF-κB and microglial activation." (PMID 39327568, 2024). "Strain WLR01 notably alleviated anxiety-like behaviors in mice, improved cognitive function, and modulated gut microbiota and gastrointestinal symptoms, potentially through the NLRP3 inflammasome and HPA axis pathways." (PMID 39339809, 2024). "Evidence suggests that activation of CB2 decreases the anxiety-like phenotype induced by chronic exposure to alcohol by inhibiting the NLRP3-driven pathway in microglia." (PMID 39065743, 2024).